EGFR (epidermal growth factor receptor)
Diseases named in the same sentence as EGFR in open-access papers (continued):
Sharing a sentence is not in itself a finding about the gene and the disease.
tumor (continued). "Furthermore, activated EGFR regulates the PI3K/AKT and MEK/ERK signaling pathways to promote EMT, whereby epithelial cells are transformed into cells with a mesenchymal phenotype by a specific program, and it is closely related to the metastasis of tumor cells." (PMID 37670265, 2023). "Furthermore, we noted increases in the expression levels of EGFR, P-ERK, GLUT1, P-mTOR, and P-4EBP in the N-WASPKOG12D mice, suggesting that the deletion of N-WASP in the keratinocytes enhanced KRas signaling and glucose uptake, resulting in aggressive tumor formation." (PMID 37760426, 2023). "Hence, these results suggested that loss of TMEM25 promotes cell growth or survival via activating EGFR/STAT3 signaling pathway, which may play a pivotal role in TNBC development, especially for the cells inside a tumor where with limited supply of growth factors." (PMID 37095176, 2023). "EGFR mutant-specific immune responses were not seen in diseased, non-vaccinated adjuvant control mice, indicating that the mice are tolerant to the transgene product and that prophylactic vaccination with Emut Vax can break this immune tolerance resulting in inhibition of tumor development." (PMID 36875137, 2023). "Finally, employing computational molecular docking studies, the authors showed that the new compounds have strong interaction with EGFR (epidermal growth factor receptor), an enzyme with tyrosine kinase domains, which is crucial for the development of non-small cell lung cancer (NSCLC) tumor cells." (PMID 36080413, 2022). "Furthermore, NLS-modified ADCs, such the epidermal growth factor receptor-positive tumor-targeting 111In-nimotuzumab-NLS, are infamous for their rapid plasma clearance and increased sequestration in normal tissues, which translate to reduced tumor accumulation." (PMID 35744930, 2022). "The observation that LATS1/2 KO by CRISPR/Cas9 confers resistance to EGFR inhibitors in vitro and in vivo indicate that YAP/TAZ reactivation by an unknown mechanism after EGFR inhibitor treatment plays an important role in HNSCC initial resistance or tumor recurrence." (PMID 36294681, 2022). "Therefore, the constitutive presence of the EGFR/NONO complex in the tumor nucleus might suggest the malignant nature of cancer." (PMID 35013116, 2022). "Indeed, the activation of EGFR produces the detachment by SRC-mediated phosphorylation of the p120/E-CAD complex from the low-density lipoprotein receptor-related protein 5/6 (LRP5/6), which together with the frizzled receptors (FZD), activates the Wnt signalosome favoring the tumor cell growth." (PMID 35267574, 2022). "Furthermore, administration of miR-16-1 via a nano-cell delivery system which is an EGFR-targeted Delivery Vehicle (EDV) of EnGeneIC in NSCLC xenograft mice models and malignant pleural mesothelioma, led to the targeted delivery in tumor and considerable tumor repression." (PMID 36071981, 2022). "In addition, in a mouse model of BC brain metastases, the administration of EGFR-CAR NK cells alone or in combination with an oncolytic herpes virus-1 resulted in more efficient eradication of tumor cells in vitro and more efficient killing of MDA-MB-231 tumor cells in an intracranial model." (PMID 36294305, 2022). "The same researchers conducted another study with the same tagged anti-EGFR antibodies with 20 patients with HNC and demonstrated that in situ tumors were associated with higher fluorescent intensities than healthy tissue, regardless of age, sex, tumor site, or size." (PMID 35884477, 2022). "Furthermore, several studies suggest that expression of EGFR is a marker of poor prognosis also in FOSCC and, accordingly, that EGFR plays a key role in tumor cells proliferation and survival, suggesting that it may be a promising molecular target in this feline cancer as well." (PMID 36467642, 2022).
tumor (continued). "However, some studies demonstrated that anlotinib directly inhibited tumor cells rather than angiogenesis, and an increasing number of unconventional pharmacologic targets have been identified, such as EGFR and c-Myc." (PMID 36614964, 2022). "Moreover, several essential pathways, such as epidermal growth factor receptor (EGFR), phosphatidylinositol 3-kinase (PI3K)/protein kinase B (PKB, Akt)/mammalian target of rapamycin (mTOR), and Ras, can regulate SREBP-1 activation to mediate tumor growth and metastasis." (PMID 35912181, 2022). "EGFR amplification was identified in two of their primary lines and was maintained in the GLICO model, but was lost in 2D adherent culture, indicating that this model may provide a more suitable tumour microenvironment to preserve the genetic characteristics of the tumour in vivo." (PMID 36611949, 2022). "Notably, ERBB2 amplification could be identified non only in tissues but also in circulating tumor DNA of CRC patients non-responsive to anti-EGFR therapy." (PMID 35582524, 2022). "Additionally, exosomal EGFR, ANXA1 and programmed cell death (PD)-1/PD-ligand 1 (PD-L1) pathway (tumor suppressor in HNSCC) have been identified as potential biomarkers for predicting prognosis and therapeutic monitoring in tumor derived exosomes of HNSCC patients." (PMID 35387114, 2022). "Therapies targeting several genes, including EGFR-TKI, ALK-TKIs, MET-TKIs, antiangiogenic therapy and immune-checkpoint inhibitors, were tested in patients with PSC, although given the rarity of the tumor type, large scale studies of any particular therapy may never be completed." (PMID 35592676, 2022). "Therefore, a plausible hypothesis is that mutations in these genes—in particular HRAS, EGFR, and RB1—were coincidental findings in individual tumours, and are not recurrent driver events in EP tumourigenesis." (PMID 34045664, 2022). "Other genomic alterations identified in this patient were EGFR A1118T, which was not an actionable driver, and CDKN2A/B loss, which was a variant of unknown significance; microsatellite status was stable, and tumor mutation burden was low (three mutations per megabase)." (PMID 35962206, 2022). "Specifically, compared with the other patients with the G719A mutation, the third patient (P5) did not experience any shrinkage of the tumor lesion after treatment, and NGS testing suggested S899N and D1083V co-mutations of EGFR; however, the significance of these co-mutations is currently unknown." (PMID 35770100, 2022). "As such, we hypothesize that additional mechanisms within the tumor microenvironment influence the accumulation of cetuximab-800CW and that the presence of EGFR may not be the only determinant, as has also been observed in EGFR-targeted photodynamic therapy." (PMID 34531264, 2022). "Thus, fusions in ROS1, RET, NTRK1 and amplifications in MET, ALK, EGFR, for example, may not be detected with circulating DNA and RNA, notably during tumor progression under treatment with TKI targeting ALK rearrangements." (PMID 33467720, 2021). "Six patients shared single EGFR hotspot mutations (L858R in five and 19Del in one), and one patient shares an other/rare mutation (TERT Amplification); each tumor also harbored an abundance of unique mutations, ranging from four to 28 mutations per tumor, with no shared additional mutations." (PMID 34109114, 2021). "Thus, when applied alone, two EGFR inhibitors, ERB and AFA, and PAL could inhibit PDX tumor growth." (PMID 34204797, 2021). "Therefore, we hypothesized that EGFR-mutant lung tumor cells upregulate murine HBEGF and that this low-affinity DTR could, if expressed at high levels, allow for sufficient DT internalization to induce tumor cell death." (PMID 34494649, 2021). "Twenty-two of them could not undergo EGFR analysis in tumor tissue because of inadequate samples." (PMID 34680416, 2021). "However, in AR negative CRPC cells, KIF15 may promote tumor cell proliferation through activating EGFR signaling pathway." (PMID 34804913, 2021).
tumor (continued). "In contrast, minimal EGFR expression and fluorescence signal were found beyond the infiltration edge (dashed lines) and in normal brain tissue, indicating panitumumab-IRDye800 is capable of delineating a histologic tumor margin and solving the problem of low negative predictive value in humans." (PMID 34158840, 2021). "Furthermore, pharmacological inhibitors of EGFR, MEK, and ERK signaling quash HPV oncogene expression and the neoplastic phenotype, revealing a potential clinical strategy to suppress uncontrolled cell proliferation, reduce oncogene expression and treat HPV neoplasia." (PMID 33481911, 2021). "Our data suggest that one promising treatment strategy for patients with concurrent EGFR and MAPK pathway activation may require alternating treatment regimens with intermittent changes between drug combinations based upon observed heterogenic tumor response and emerging resistance patterns." (PMID 34921211, 2021). "Finally, CMS3 tumours most resemble the CRIS-A subtype, lacking immune and inflammatory signatures and often harbouring KRAS-activating mutations, which confer resistance to anti-EGFR therapies." (PMID 33673710, 2021). "Indeed, it has been reported that high mannose forms of EGFR expressed on the cell surface of several lung cancer cell lines were specifically recognized by an endogenous lectin, surfactant protein D, leading to downregulation of EGF signalling and consequently tumour-suppressive effects." (PMID 33671245, 2021). "Additionally, EGFR inhibitors efficacy is not solely based on their direct effects on tumor cells, but also may act on the regulation of tumor microenvironment." (PMID 33918490, 2021). "Notably, the difference in expression between SOCS5 and EGFR of tumor tissue was negatively correlated with that of corresponding normal tissue in about half of the tissue sets (30/62, 48.4%) which revealed the possible negative regulating role of SOCS5 in EGFR expression." (PMID 33758600, 2021). "However, Misale found that in vitro and in vivo, the growth of resistant cells could not be hampered by MEK1/2 inhibitors alone; instead, the synergistic pharmacological blockade of EGFR and MEK induced drawn-out ERK inhibition and serious growth impairment of resistant tumour cells." (PMID 34663410, 2021). "Sym004, a novel 1:1 mixture of two nonoverlapping anti-EGFR mAbs, showed significant advantages of abrogating EGFR ligand-induced phosphorylation and suppressing downstream signalling of all individual EGFR mutants both in cetuximab-resistant cell lines and in a tumour xenograft model." (PMID 34663410, 2021). "In addition, epidermal growth factor receptor (EGFR), mammalian target of rapamycin (mTOR), vascular endothelial growth factor (VEGF), fibroblast growth factor (FGF) and their downstream pathways are triggered in PAs, thereby modulating tumor cell proliferation, migration and/or tumor angiogenesis." (PMID 35011868, 2021). "Concerning the central role of EGFR and PD-L1 in the pathogenesis and therapy of HNSCC, hypoxia-mediated modulation of receptor tyrosine kinase signaling or the immunologic status might represent another paradigm for therapy resistance mediated by tumor microenvironmental traits." (PMID 33718186, 2021). "Interestingly, amplification of EGFR was only identified in the recurrent but not in the primary tumor, suggesting that this might be a crucial event in the evolution of this tumor." (PMID 34399808, 2021).
tumor (continued). "The considerable heterogeneity of EGFR CNG and protein over-expression observed in ESCC may be a key determinant of resistance, with rapid selection and outgrowth occurring of EGFR CNG and protein overexpression-negative tumour cell sub-clones that are unresponsive to EGFR inhibitors." (PMID 33169187, 2021). "The oncogenic function of PSAT1 has been investigated in many tumor types and has been found to play a role in the proliferation, migration, and chemo-resistance yet it remains elusive whether PSAT1 may contribute to the cellular response to specific oncogenic signaling, particularly EGFR." (PMID 34439090, 2021). "In the present this study, having excluded the presence of mutations in EGFR or KRAS by highly specific and sensitive techniques in the primary tumor, we are able to confirm that the mutations detected in other lung cells were not the result of contamination from the tumor." (PMID 34257550, 2021). "Furthermore, in the absence of TMEM16A co-targeting, tumor cells may acquired resistance to EGFR/HER inhibitors." (PMID 33681289, 2021). "However, no research has focused on whether the anti-tumour metastasis activity of EGFR-TKIs occurs through inhibiting lymphangiogenesis in NSCLC." (PMID 31892990, 2020). "Since inflammation in the tumour microenvironment is commonly modulated to benefit the tumour, and the observed complement activation was not due to apoptosis of EGFR inhibited cells, we hypothesize that cancer cells may modulate complement activation during growth inhibitory conditions." (PMID 32054454, 2020). "Therefore, we examined EGFR expression and inhibition in TNBC preclinical cell lines to determine if EGFR promoted resistance to prexasertib and if inhibition of EGFR could enhance the anti-tumor activity of prexasertib in TNBC tumors." (PMID 35582228, 2020). "Loss of responsiveness to EGFR-TKIs in NSCLC with non-T790M EGFR mutation can be explained in terms of EGFR-TKI-resistant ALDH1A1bright/CD44high CSC that evolutionally possesses drug resistance and is often referred to as a tumor-initiating cell and associated with EGFR-TKIs non-responder." (PMID 32293355, 2020). "Moreover, the growth factor family receptors (e.g. EGFR, VEGFR) can also induce the FAK/Src/MAPK activation in an integrin-independent manner, suggesting that targeting FAK may provide an ancillary effect to inhibit the growth of tumor cells." (PMID 33026975, 2020). "Epidermal growth factor receptor (EGFR) is not mutated but overexpressed in MPM, leading to deregulation of EGFR signaling and aberrant activation of downstream pathways such as RAS/RAF/MAPK and PI3K/AKT/mTOR, which in turn promotes cell proliferation, tumor invasiveness and angiogenesis." (PMID 33072611, 2020). "In summary, depending on the tumor type, PTPN13 may regulate resistance to anti-cancer therapies through its anti-apoptotic role via the FAS pathway, or through regulation of secondary EGFR pathways (ephrinB1/ErbB and SRC/PKD1/AKT), or through an indirect action on microtubules mediated by ephrinB1." (PMID 33322542, 2020). "Furthermore, the anti-tumor activities of type I IFNs can be limited by the activation of several survival pathways, such as the induction of the JAK2/STAT-3 pathway, the activation of nuclear factor kappa-beta (NF-κB) and the increased expression of the epidermal growth factor receptor (EGF-R)." (PMID 32967656, 2020). "However, other modes of action of PTPRK, such as dephosphorylating other signaling factors like β-catenin, EGFR, or STAT3, or cell junction proteins, may also contribute to its tumor-suppressive function." (PMID 31934854, 2020). "However, given the initially counter-intuitive observation of lower efficacy of the ADC on the higher EGFR-expressing PANC-1 tumour, density of expression alone may not correlate with improved ADC efficacy." (PMID 32913288, 2020).
tumor (continued). "Also, EGFR expression is not present when one of those markers are expressed, suggesting that in patients’ samples these three mechanisms are independently activated by tumour cells." (PMID 32362655, 2020). "Yet, the combination of radiotherapy with the epidermal growth factor receptor (EGFR) binding antibody cetuximab has shown efficacy and EGFR expression has been associated with poor survival, preferentially in non-accelerated schedules arguing for a role in tumor repopulation." (PMID 31998639, 2019). "The tumor response for cytotoxic chemotherapy as the first-line treatment could be evaluated in 86 patients (TTF-1 positive, 59 cases; TTF-1 negative, 27 cases; EGFR mutation, 2 cases)." (PMID 31196060, 2019). "However, it is unclear whether such mechanisms would be in play in EGFR mutant tumor cells that are undergoing apoptosis but rather in EGFR wild-type tumor cells where erlotinib does not lead to cell death." (PMID 31291990, 2019). "Based on the duration of disease control, the evolution of the tumor burden, and clinical symptoms, regardless of genotype profile, the diversity of EGFR TKI failure could be categorized into three modes, including dramatic progression, gradual progression, and local progression." (PMID 29455650, 2018). "Basically, there are two situations were MET testing could help treatment decision: patients with a non-KRAS, BRAF, EGFR, or HER2 tumor for which the identification MET as a driver could lead to specific treatment and patients with EGFR mutated tumors secondary resistance." (PMID 29890761, 2018). "Furthermore, rechallenging of the mice that rejected the tumor upon treatment with EGFR-targeted 4-1BB-agonistic trimerbody with fresh CT26mock cells failed to allow tumor implantation, thus indicating that long-lasting tumor-specific memory had been established." (PMID 30442944, 2018). "After immediate withdrawal, the disease has the possibility of outbreak, and targeted therapy is still effective after treatment interruption, which may be due to drug-resistant tumor cells still exist in a certain proportion of cells sensitive to EGFR-TKI, but the specific mechanism is not clear." (PMID 29455664, 2018). "CHMFL-ALK/EGFR-050 showed potent anti-tumor activity in pre-clinical NSCLC models driven by either mutant EGFR or ALK, but whether or not it will be suitable for NSCLC patients and a less toxic alternative for patients with dual ALK/EGFR overactivity, remains to be determined." (PMID 29455675, 2018). "Taken together with the identification of EGFR and MYC amplification in cold tumours, our analysis suggests that pharmacological inhibition of EGFR/mTORC1/MYC-driven glycolysis could be an effective means by which to ‘warm-up’ these tumours and potentially enhance responses to ICB." (PMID 30104673, 2018).